RBM5 (RNA binding motif protein 5)
Diseases named in the same sentence as RBM5 in open-access papers (continued):
Sharing a sentence is not in itself a finding about the gene and the disease.
tumor (continued). "Since RBM10 would no longer influence cellular processes, RBM5 could exercise its RBM10v2-independent tumor-suppressor properties." (PMID 28662214, 2017). "And RBM5 expression was clinically correlated with tumor stage but not sex." (PMID 28061901, 2017). "Previously, we have proved that RBM5 expression was not directly regulated by EGFR, however, the results in the current study indicate that RBM5 might manipulate EGFR expression as an upstream gene, which may be a predominant mechanism by which RBM5 mediates tumor suppression." (PMID 25441176, 2014). "However, RBM5 and KRAS expression was not an independent factor associated with a higher rate of tumor recurrence." (PMID 23425895, 2013). "Similarly, when the bands were quantitatively compared, the expression of RBM5 protein was found to be lower in tumor compared to the non-tumor counterpart in the majority of the paired samples (except in 7 of the 30 patients)." (PMID 22866867, 2012). "Furthermore, the reduced RBM5 protein expression correlated with smoking status, tumor stage and lymph node metastasis of NSCLC, while overexpression of EGFR and KRAS proteins correlated with tumor stage and lymph node metastasis of NSCLC." (PMID 22537942, 2012). "However, neither low RBM5 expression nor high KRAS expression were proved to be an independent factor associated with higher recurrence rate when corrected with age, gender, tumor size, lymphatic involvement, distant metastasis, cell differentiation, UICC stage and nerve and venous invasion." (PMID 23425895, 2013). "Hemizygous total body RBM5 gene deleters administered the potent cigarette-smoking carcinogen, 4-(methylnitrosamino)-1-(3-pyridyl)-1-butanone (NNK), had increased tumor burden by 48 weeks, but not earlier." (PMID 32765218, 2020).
cancer (35 papers, 2006 to 2025). A tumor composed of atypical neoplastic, often pleomorphic cells that invade other tissues. "For example, while AS-NMD is used for the inhibition of RBM10 to RBM5, RBM5 also controls the expression of RBM10 splicing variants in turn through AS-NMD to reduce the action of cancer promotion." (PMID 40275278, 2025). "That deletion of the region encompassing the RBM5 gene is one of the earliest lesions associated with smoking does suggest that downregulation of RBM5 is necessary for cancer initiation events." (PMID 22537942, 2012). "The RNA-binding motif protein RBM5 belongs to a family of multi-domain RNA binding proteins that regulate alternative splicing of genes important for apoptosis and cell proliferation and have been implicated in cancer." (PMID 37454201, 2023). "We evaluated 6 splicing factor mutations commonly observed in cancer, including hotspot mutations in SF3B1K700E, U2AF1S34F, and CRISPR-engineered loss of function in FUBP1, RBM5, RBM10, and ZRSR2." (PMID 41279721, 2025). "Previous studies in different cancer types suggested RBM5 as a potential target to prevent tumorigenesis." (PMID 35552415, 2022). "This included increased levels of caspases and FAS (both which were previously reported to be regulated by RBM5 in cancer cells)." (PMID 32765218, 2020). "The history of investigations on RBM5 in cancer is relevant here because the large body of foundational work in that field is important to understanding its possible neurotoxicity in the brain." (PMID 32765218, 2020). "On the other hand, in vitro CNS injury studies support the notion that RBM5 increases neuronal vulnerability to an insult, much like its effect on cancer cells to augment cell death after exposure to chemotherapeutic agents." (PMID 32765218, 2020). "Recent studies showed that RBM5 is regulated by long noncoding RNAs (lncRNAs) or miRNAs in cancer cells." (PMID 32947864, 2020). "Modulation of RNA splicing is a key mechanism by which RBM5 inhibits the proliferation and survival of cancer cells." (PMID 32765218, 2020). "At the same time, RBM5 was shown to antagonistically regulate the proliferative ability of cancer cells through alternative splicing of NUMB gene." (PMID 28061901, 2017). "Overall, our data revealed that the pro-survival autophagy is enhanced by ectopic RBM5 overexpression, and inhibition of autophagy can enhance RBM5-induced apoptosis and increase cancer cells sensitivity to cisplatin." (PMID 26923134, 2016). "Among these 10 hubs are 5 – ACP1, HSP90AA1, LEF1, MLH1, and RBM5 - common to the major identified cancer-related pathways." (PMID 27809917, 2016). "Consistently, several splicing factors were found to be mutated or significantly changed in expression between cancers and normal tissue, including SRSF1, QK1, RBM4, RBM5/6/10, and hnRNP A2." (PMID 25749525, 2015). "Several studies have showed that RBM5 is differentially expressed in human cancers and is involved in tumorigenesis." (PMID 23425895, 2013). "RNA-binding motif protein 5 (RBM5) is a gene which maps to human chromosome 3p21.3, a critical region which is deleted in a large number of human cancers and which is predicted to contain one or more tumor suppressor genes (TSGs)." (PMID 23158838, 2012). "It is still a debate on how genes transcribed from the RBM5 locus functioned in cancers." (PMID 38216972, 2024). "Our study showed that RBM5 upregulation could suppress cancer cell proliferation and migration mediated by the CHIP–eIF2α pathway." (PMID 38272235, 2024). "Our findings support a growing body of evidence that, in brain, RBM5 preferentially modulates proteins linked with brain function, unlike its role in cancer." (PMID 37848418, 2023). "RBM5, RBM6, and RBM10 are commonly deleted, mutated, and/or under-expressed or overexpressed genes in many cancers; however, they have different roles in in vitro colony formation assays, partially due to their antagonistic regulation of NUMB alternative splicing." (PMID 36006412, 2022).
cancer (continued). "The mechanisms mediating increased vulnerability between neurons vs. cancer cells may differ based on differences in the genes that are affected by RBM5 inhibition." (PMID 32765218, 2020). "RBM5 mediated pro-death signaling pathways have been well characterized in cancer, and has resulted in increased recognition that its modulation may have therapeutic utility in the CNS." (PMID 32765218, 2020). "The focus of cancer research on RBM5 is the result of its location in the 3p21.3 gene cluster." (PMID 32765218, 2020). "We consider the evidence that RBM5 is particularly attractive for that purpose because it promotes cell death in cancer cells and in neurons, and finally, discuss new evidence on its novel gene targets in the CNS, which has opened the door to new avenues of translational research." (PMID 32765218, 2020). "It seems that both overexpression and downexpression of RBM5 influence the progression of cancer." (PMID 33584809, 2020). "Most studies reporting on RBM5 mediated mechanisms that regulate cell death were done in cancer." (PMID 32765218, 2020). "Cumulative data from RNAi studies to elucidate genes and/or their splicing regulated by RBM5 in human neuronal-like cells, immature primary rat cortical neurons, and intact brain tissue in adult mice, increasingly suggest that RBM5 plays a distinct role in the CNS vs. its role in cancer." (PMID 32765218, 2020). "As RBM5 is downregulated in many cancers, this work is particularly meaningful." (PMID 28662214, 2017). "Similarly, the effect of culture medium on prior studies of RBM5 in cancer cells could impact the observed gene-splicing targets." (PMID 32765218, 2020). "Furthermore, the inhibition of autophagy enhanced RBM5-induced cell death and increased cancer cell sensitivity to cisplatin in A549 cells, maybe through enhanced apoptosis." (PMID 26923134, 2016). "However, diverse effects of RBM5 have been revealed in human cancers." (PMID 23425895, 2013). "Studies have shown that ESPR1 and RBM5 play an important role in the event of alternative splicing in cancer 42, 43, and the results of GESA also show that ESRP1 and RBM5 are significantly enriched in the spliceosome pathway." (PMID 33976726, 2021). "Of the eight modeling RBPs, half were upregulated including PABPC1, PRPF6, OAS1, IPO7, and half were downregulated including RBM5, RBM6, LSM12, and FXR7 in cancer cases." (PMID 33584809, 2020). "To further test whether RBM5 expression might correlate with AML development, we analyzed the public RNA-seq data from the TCGA clinical cancer sample datasets." (PMID 38216972, 2024). "Subsequent analysis of subgroups of patients with different clinical variables in the TCGA cohort showed that ESRP1 and RBM5 parts showed prognostic differences, but this does not mean that the results are biased, which may be due to data bias, population susceptibility and cancer heterogeneity." (PMID 33976726, 2021). "Recent reports in cancer cells found that the RRM domains in RBM5 (but not the two ZF domains) were necessary for its pro-death functions." (PMID 32765218, 2020). "We identified that the expression change of MIR381 (p-value < 0.83) contributes to the expression changes of RNA-binding protein 5 (RBM5) (p-value < 0.008) and ubiquitin specific peptidase 15 (USP15) (p-value < 6☓10-4) via significant miRNA regulations (p-value < 10-16) in cancer cells." (PMID 26897165, 2016). "This suggested that RBM5 might preferentially regulate genes involved in neurotransmission in the CNS rather than pro-death genes as reported in cancer." (PMID 32765218, 2020). "RNA binding protein RBM5/6 and 10 could differentially control alternative splicing of a negative Notch regulator gene NUMB, thus antagonistically regulating the Notch signaling activity for cancer cell proliferation." (PMID 27536874, 2016).
cancer (continued). "The lack of studies on the role of RBM5 in healthy tissues has led to a paucity of data on its targets in non-transformed cells, and whether or not they differ or overlap from those reported in cancer." (PMID 32765218, 2020). "This duality is not surprising, as splicing factors such as RBM5 and ESPR1/2 have been found to have contrasting roles in different cancer contexts." (PMID 39034402, 2024).
neurodegenerative disease (2 papers, 2020 to 2023). A disorder of the central nervous system characterized by gradual and progressive loss of neural tissue and neurologic function. "Here, our data suggest that RBM5 may have a role in directly regulating the expression and splicing of transcripts relevant to neurodegenerative diseases, supporting a role for RBM5 in neurodegeneration via other pathways than apoptosis." (PMID 37468457, 2023).
cardiovascular diseases (1 paper, 2021). "At least 6 critical genes, namely CTNNB1, HNRNPA1, SRSF4, TRA2A, SFPQ, and RBM5, and two large clusters of biological terms which are associated with the cardiovascular diseases are deregulated in the presence of omeprazole." (PMID 34659661, 2021).
infection (1 paper, 2022). The state of being infected such as from the introduction of a foreign agent such as serum, vaccine, antigenic substance or organism. "We propose that this phenomenon, which is visible on the micrometer scale following the overexpression of RBM5 and InlP, could take place at a smaller scale under physiological conditions (i.e., infection by L. monocytogenes in vivo)." (PMID 36535993, 2022).
RBM5 also shares sentences with these, for which no sentence is quoted: adenocarcinoma (3 papers); Vestibular schwannoma (2); acute leukemia (1); alcohol dependence (1); bacterial infection (1); brain injury (1); breast adenocarcinoma (1); chronic myelomonocytic leukemia (1); COVID-19 (1); duodenitis (1); gastritis (1); injury (1); lymphoblastic leukemia (1); myelodysplastic syndrome (1); ovarian carcinoma (1); primary immunodeficiency (1); psoriasis (1); serous ovarian cancer (1); skeletal muscle tumour (1); sterility (1); Stroke (1).